IL1B (interleukin 1 beta)
Diseases named in the same sentence as IL1B in open-access papers (continued):
Sharing a sentence is not in itself a finding about the gene and the disease.
gout (continued). "Some studies suggest that MSU crystals can activate autophagy and enhance autophagy activity at the basal level, while inhibiting autophagy increases the level of IL-1β, suggesting that autophagy may negatively regulate gout inflammatory responses that are unique to eukaryotic cells." (PMID 37069596, 2023). "Hence, gout has been recognized as a prototype I IL-1β mediated autoinflammatory disease." (PMID 36896178, 2023). "Thus, mitochondrial dysfunction may lead to changes in the mitochondrial membrane potential, release of mitochondrial ROS, and other mechanisms that activate the NLRP3 inflammasome and contribute to the release of IL-1β to promote gout progression." (PMID 35464445, 2022). "Moreover, intraarticular angiotensin II administration also induced inflammatory parameters, that are also the clinical features of gout in humans, such as edema, neutrophil infiltration and IL-1β release, all of which were prevented by specific AT2R antagonism." (PMID 36173505, 2022). "Therefore, dapansutrile may reduce the chemotaxis and activation of inflammatory cells for the treatment of gouty arthritis by blocking the activation of IL1B, CXCL8, and TNF." (PMID 36105284, 2022). "Therefore, it supports the argument of the pivotal role of IL-1β in the pathogenesis of gout." (PMID 35370689, 2022). "Furthermore, in a mouse gout model by intraarticular MSU injection, mice deficient in NLRP3, caspase-1, or ASC showed much reduced pain response as well as reduced neutrophil infiltration and IL-1β in ankle joints." (PMID 33785039, 2021). "Importantly, our work using this mouse model of gout as well as RA models enabled us to develop a framework in which complex cellular interactions are required to account for the counter-regulatory effects mediated by type I IFNs on IL-1β." (PMID 34066649, 2021). "Thus, the inhibition of IL-1β is able to downregulate the inflammatory responses related to gout." (PMID 35095497, 2021). "Importantly, the massive release of IL-1β is deemed as an early feature of gout." (PMID 33967792, 2021). "This might help account for the therapeutic efficacy of an IL-1β blocking agent in treating gout." (PMID 33493135, 2021). "Monosodium urate crystal is the causative factor of gout, which can activate a variety of immune cells to release proinflammatory cytokines such as tumor necrosis factor-alpha (TNF-α) and interleukin-1 beta (IL-1β), thereby inducing the production of gouty arthritis." (PMID 34803702, 2021). "This is consistent with a previous report using monosodium urate (MSU) crystal-induced gout in mice which showed that pre- or post-treatment with Ac2-26 reduces the migration of neutrophils into the synovial cavity, as well as the production of IL-1β in synovial tissue." (PMID 33440601, 2021). "At present, several clinical studies have proven that therapies targeting against IL-1β are successful strategies for relieving pain, inflammation, and recurrent attacks of gout, indicating that targeting IL-1β and its related pathways is effective for gout treatment." (PMID 33785039, 2021). "Consequently, inhibiting the formation and activation of inflammasomes and proinflammatory cytokines, such as TNF-α and IL-1β, is an important therapeutic strategy to alleviate swelling, pain, and inflammation in inflammatory diseases, including gouty arthritis." (PMID 34284768, 2021). "Consequently, hypomethylated JNK1 might contribute to increased JNK1, accentuating IL-1β production in macrophages and presenting as gout clinically." (PMID 32630231, 2020). "However, despite the discovery of the NLRP3 inflammasome and its role as a Pattern Recognition Receptor linking the detection of a danger signal (MSU) to IL-1β secretion in vitro, the precise mechanisms leading to joint inflammation in gout patients are still poorly understood." (PMID 32104502, 2020).
gout (continued). "Similarly to TGF, the natural inhibitor of IL-1β, IL-1Ra, and IL-10 might have a key role in the resolution phase as its levels increase in SF of patients with gout and following MSU injection in mice." (PMID 32426360, 2020). "Therefore, the enhanced TRPA1 channel functional activity we observed may be due to channel expression upregulation mediated by IL-1β, IL-6 or other inflammatory mediators released during gout." (PMID 33204337, 2020). "However, the increase of serum IL-1β levels was found to be reduced in rats treated with chicory extract (15 or 7.5 g/kg) and colchicine, which suggests the effect of chicory extract on inhibiting inflammation related to gout." (PMID 31590257, 2019). "This ability to buffer against changes in oxidative stress points to the presence of many mechanisms that operate in concert to control redox status and explains why changes in serum uric acid alone is not sufficient to cause release of IL-1β and contribute to development of gout." (PMID 30761138, 2019). "Moreover, treatment with anakinra (a recombinant IL-1 receptor antagonist) or a monoclonal antibody that blocks IL-1β caused the partial inhibition of NET formation by neutrophils treated with synovial fluid from patients with gout, further supporting a role for IL-1β in the formation of NETs." (PMID 28303140, 2017). "With respect to investigational agents, randomized clinical trials of the IL-1β-specific monoclonal antibody canakinumab have demonstrated superiority compared to a single dose of 40 mg triamcinolone acetonide in reducing pain in acute gout and delaying time to next acute gout flare." (PMID 28818081, 2017). "Berberine may influence the NLRP3 inflammasome which is involved in MSU crystals-induced innate immune responses, attenuate the expression of NLRP3, further inhibit downstream signalling molecular IL-1β, and eventually play a role in treatment of gouty arthritis." (PMID 27689075, 2016). "Finally, NET-bound IL-1β may be one of the targets of anti-IL-1β therapies, such as canakinumab which targets bioactive IL-1β in FMF or gout patients." (PMID 28123386, 2016). "In addition, the current study suggests that the release of IL-1β by synovial fibroblasts also may be of importance in the pathophysiology of gout." (PMID 25897296, 2015). "The T allele of CARD8 rs2043211 (C10X) has been associated with increased risk of gout in Chinese, and rs2149356 in toll-like receptor 4 (TLR4), a receptor functionally implicated in MSU-stimulated inflammation, has also been associated with serum IL-1β levels and the risk of gout in Han Chinese." (PMID 26462562, 2015). "We also found that IL-1β, a proinflammatory cytokine involved in the pathogenesis of gout and also a preresorptive cytokine for bone metabolism, might be a potent mediator in the activation of osteoclasts, which results in the bone erosion seen in gout." (PMID 26347587, 2015). "A large number of studies have shown that cysteinyl aspartate specific protease-1 (CASP1) played an important role in the inflammatory response of primary gout, but the decreased expression of different CASP1 transcript variant could inhibit the activation of IL-1β." (PMID 26557856, 2015). "In addition, IL-1β can induce the expression of a wide range of cytokines and chemokines like TNF-α, IL-6, IL-17, and MCP-1 that are directly responsible for the influx of neutrophils into the synovium, a hallmark of gouty arthritis." (PMID 26709520, 2015). "Since neutrophils play a major role in gout we sought to determine whether their activation may involve the formation of proinflammatory neutrophil extracellular traps (NETs) in relation to autophagy and IL-1β." (PMID 22195044, 2011). "Corresponding in vivo findings confirmed reduced levels of IL-1α, IL-1β, IL-6, TNF-α, and PGE2 in the synovial fluid, suggesting efficacy in controlling the acute inflammatory phase of gout attacks." (PMID 40649931, 2025).
gout (continued). "To explore the role of TLRs and key cytokines in gout pathogenesis, we reanalyzed a publicly available dataset, focusing on the expression of TLRs, IL-1β, IL-18, TNF-α, IL-10, and TGF-β in patients experiencing gout flare versus remission." (PMID 41583461, 2025). "In the gout state, aberrant FXR activation and pro-inflammatory cytokines (IL-1β, and TNF-α) suppress BA synthesis." (PMID 41255527, 2025). "The initiation of acute gout is well-characterized by MSU crystal-induced NLRP3 inflammasome activation, leading to IL-1β release and NET-driven inflammation." (PMID 41190022, 2025). "For example, in a murine model of gouty arthritis, the compound was found to inhibit the IKK/NF-κB/TXNIP axis, leading to downregulation of NLRP3 and pro-IL-1β expression, ultimately attenuating inflammation and monocyte infiltration." (PMID 41463396, 2025). "Another instance involves Simiao Powder, where compounds like quercetin target key inflammatory proteins such as IL-1β and TNF, modulating the NLRP3 inflammasome pathway to reduce gout-related inflammation." (PMID 41019543, 2025). "In a gout model using THP-1 cells treated with MSU at different time points, varying degrees of upregulation in IL-1β and IL-6 proteins were observed over time." (PMID 40170729, 2025). "Elevated serum levels of TNF-α, IL-6, and IL-1β are commonly observed in HUA and gout patients, reflecting inflammasome activation and immune dysregulation." (PMID 40870677, 2025). "Canakinumab is an anti-IL-1β antibody therapy that is FDA-approved for Still’s disease, periodic fever syndrome, and gout flares." (PMID 40002768, 2025). "Kim found that gout patients showed a higher expression of CXCL12 and proinflammatory cytokines, including IL-1β and IL-18, than members of the control group." (PMID 40444241, 2025). "In the final stage, hyperuricemia combined with gouty arthritis, MSU crystals were deposited in joint synovial fluid after 30 days of intervention, and the inflammatory factor IL-1β levels were elevated in both serum and synovial fluid." (PMID 40771212, 2025). "Treatment with a miR-20b inhibitor significantly increased NLRP3 protein levels and IL-1β and TNF-α secretion in MSU-stimulated THP-1 cells, indicating that miR-20b negatively regulates NLRP3 in an in vitro gouty arthritis model." (PMID 41311848, 2025). "Colchicine, that has been the drug of choice for gout attack for more than 200 years, that blocks MSU crystal-induced IL-1β generation upstream of NLRP3 inflammasome activation possibly by suppressing the microtubule-mediated NLRP3 inflammasome assembly." (PMID 39968300, 2025). "The upregulation of genes like”IL1B”and”CXCL2”in CD14+ monocytes further supports their involvement in the activation of the NLRP3 inflammasome, a critical pathway in gout pathogenesis." (PMID 40370447, 2025). "Indicatively, IL-1b-coated NETs have been detected in both autoinflammatory diseases, such as familial mediterranean fever (FMF), and common diseases, such as gout, and their presence influences the immunopathology of these disorders." (PMID 40565198, 2025). "The expression levels of IL-1β, IL-6, JAK2, and STAT1/3 mRNA were significantly lower in the gout group compared to the HC group (all P < 0.001)." (PMID 40170729, 2025). "In gout, it`s a key factor that S100A9 drives the production of sodium urate crystals and further induces the secretion of IL-1β in pathogenesis." (PMID 38448514, 2024). "Our study found that deZP administration reduced paw thickness, a symptom of acute gouty edema, and decreased IL-1β mRNA and protein levels in an MSU-induced gouty arthritis animal model." (PMID 39861092, 2024). "Gouty arthritis results from monosodium urate (MSU) crystal deposition in joints, initiating (pro)-interleukin (IL)-1β maturation, inflammatory mediator release, and neutrophil infiltration, leading to joint swelling and pain." (PMID 38474000, 2024).
gout (continued). "In mouse BMDMs, ER can specifically inhibit the activation of caspase-1 and the secretion of IL-1β by inhibiting ASC oligomerization, suggesting its potential as a treatment for HUA and gout." (PMID 38708084, 2024). "Endogenous stimulatory factors such as MSU crystals can induce the body to produce a large amount of IL-1β and other inflammatory factors by activating the NLRP3 inflammasome signaling pathway, thereby inducing gouty arthritis." (PMID 39544522, 2024). "The target genes of Terpine-4-ol, a main compound of ZP, were overlapped with the gouty arthritis-related genes such as NLRP3, PTGS2, CXCL8, IL6, TNF, IL1B, TLR4, and ALB." (PMID 39861092, 2024). "In gouty arthritis, MSU activates the NLRP3 inflammasome through the priming signal of NF-κB-dependent transcription of NLRP3 and pro-IL-1β, which triggers a downstream signal upon activation of the TLR 4 receptor." (PMID 39861092, 2024). "During gout flare-ups, the JAK2/STAT3 signaling pathway is activated, leading to increased expression of cytokines such as IL-6, IL-1β, and TNF-α in both the kidneys and joints." (PMID 39611154, 2024). "We evaluated the relationship among IL-1β, IL-18, CXCL12, CXCR4, and the laboratory variables in the patients with gout." (PMID 36979628, 2023). "Parallel to the localized joint gout flare, our current work revealed that circulating CMs, IMs, and DCs were highly enriched in proinflammatory factors, such as NLRP3, IL-1B, and TNF, which exhibited relatively low expression in blood NCMs and other PBMCs." (PMID 38063198, 2023). "Subsequently, neutrophils extracted from patients with gouty arthritis were induced to form NETs by MSU crystals and added to the medium containing IL-1β, MCP-1, TNF and IL-6." (PMID 37810893, 2023). "During the initiation phase of a gout flare, the NLRP3 inflammasome mediates the production of mature IL-1β and appears to be important." (PMID 37996809, 2023). "In peripheral blood mononuclear cell-derived macrophages obtained from gout patients, we observed a synergistic effect of ATP on MSU crystal-induced IL-1β release." (PMID 36686377, 2023). "We found that gout patients showed a higher expression of CXCL12 and proinflammatory cytokines, including IL-1β and IL-18, than members of the control group." (PMID 36979628, 2023). "In a rat gouty arthritis model established by injecting MSU crystals, LJP-1 ameliorated the degree of ankle swelling in rats and decreased the IL-1β, IL-6, TNF-α, and cyclooxygenase-2 (COX-2) levels in the serum, eventually alleviating gouty arthritis." (PMID 37375383, 2023). "In an attempt to search for new therapeutics for treatment of gout attacks, we investigated the regulatory potentials of the wild rice-derived peptide, R14 on MSU crystals-induced secretion of IL-1β in macrophage cells." (PMID 37197585, 2023). "Patients with RA had higher plasma levels of sTNFR1, IL-1β, IL-12p70, TNF and IL-6, compared to OA and gout patients (all, P < 0.05)." (PMID 37202736, 2023). "Colchicine has been shown to have several mechanisms of action in the treatment of gout, including inhibiting the activation of the NLRP3 inflammasome, blocking the release of IL-1β." (PMID 37881185, 2023). "During gout flare-ups, the activation of JAK2/STAT3 signaling results in an elevation of cytokine expression, including IL-6, IL-1β, and TNF-α, within the kidneys and joints." (PMID 38094893, 2023). "Therefore, blocking or antagonizing IL-1β could be a new target for gout treatment." (PMID 37478249, 2023). "Plasma levels of pro-inflammatory cytokines IL-1β, IL-6, IL-12p70 and TNF were elevated in RA patients in contrast to OA and gout, with significant differences between RA and OA groups (p < 0.05)." (PMID 37202736, 2023). "In the present study, we confirmed that the IL-1β and IL-18 expression was increased by a stimulation with MSU crystals as well as in the blood of gout patients, together with CXCR4 and CXCL12." (PMID 36979628, 2023).
gout (continued). "In humans, IL-1β production by resident macrophages is stimulated by MSU crystals, and plays a crucial role in the pathogenesis of gout." (PMID 35154099, 2022). "In our study, high levels of IL-1β, IL-6 and TNF-α were observed in LPS and MSU induced gout in THP-1 cells, which means gout model in vitro was successful." (PMID 35462936, 2022). "The gout inflammatory response initiates during phagocytose of MSU crystals by resident macrophages with subsequent activation of the inflammasome, IL-1β, and other pro-inflammatory cytokine release." (PMID 36496970, 2022). "Acute gout attacks depend on the activation of macrophage TLRs/NF-κB signaling pathway (signal 1) and NLRP3 inflammasome complex/IL-1β (signal 2) dual signaling pathways." (PMID 35464862, 2022). "The levels of IL-1β, TNF-α and TGF-β1 in the serum of rats were used as indicators to evaluate the effect of MBD on gouty arthritis rats." (PMID 36589463, 2022). "For example, miR-223-3p and miR-22-3p reduce the production of IL-1β by targeting NLRP3, thereby alleviating the inflammatory response of gout." (PMID 36339582, 2022). "Compared with the CON group, the content of IL-8, TNF-α, IL-1β, NF-κB, UA in serum and ESR from the MOD group were increased, and IL-10 content were decreased indicating that the acute gouty arthritis model of animals was successfully built." (PMID 36090056, 2022). "Acute gout flare is induced by NLRP3 inflammasome activation and the consequent conversion of pro-IL-1β and pro-IL-18 into the active forms of IL-1β and IL-18." (PMID 36430392, 2022). "When the quail showed gout symptoms, the NLRP3 inflammasome was activated, and the expressions of IL-1β, TNF-α, IL-6, IL-8, and IL-18 were significantly increased." (PMID 36569836, 2022). "Similar to RA patients, the serum and synovial fluid samples of the patients with gout were detected to contain higher levels of NLRP3, caspase-1, IL-1β, and IL-18." (PMID 35629398, 2022). "The upregulation of miR-488 inhibits monosodium urate-induced expression of IL-1β proteins in THP-1 cells and plays a posttranscriptional regulatory role in gouty arthritis." (PMID 35186188, 2022). "NLRP3 inflammasomes activate IL-1β by activating caspase-1 and then activate the NOD receptor family signaling pathway to induce gout inflammation." (PMID 35449811, 2022). "While screening for flavonoids with anti-gout effects, Hao found that luteolin can ameliorate hyperuricaemia and acute gouty arthritis by reducing the levels of inflammatory factors (TNF-α, IL-1β) in rats." (PMID 35924042, 2022). "In the context of gout, we have previously shown that PP2A knockdown in human THP-1 monocytes exacerbated IL-1β release in response to urate crystal stimulation." (PMID 36467056, 2022). "An ABCG2 SNP (rs2231142) enhances this autophagic impairment, diminishes the formation of neutrophil extracellular traps, and aggravates gout via the overactive release of the NLRP3 inflammasome and IL-1β." (PMID 35813212, 2022). "Plasma from healthy subjects was used as a specificity control for the assay, which confirmed the presence of IL-1β and ASC in gout synovial fluids." (PMID 36225929, 2022). "In the air pouch mice model of gout, MSU induced less amounts of IL-1β and chemokines secretion, an increased M2/M1 macrophage ratio, and a reduction of neutrophil recruitment in DcR3-transgenic mice, which expresses DcR3 in myeloid cells." (PMID 33746978, 2021). "IL-1β, an indicator of gout inflammation, plays a key role in MSU-induced initiation and progression of acute gout flares." (PMID 33959014, 2021). "Canakinumab is a human monoclonal antibody that targets IL-1β approved for the treatment of CAPS and is undergoing clinical trials for chronic obstructive pulmonary disease (COPD) and gout." (PMID 33534121, 2021). "An important feature of gouty arthritis is the activation of NLRP3 inflammasome and the release of IL-1β." (PMID 33505510, 2021).